BMI1 (BMI1 proto-oncogene, polycomb ring finger)
Diseases named in the same sentence as BMI1 in open-access papers (continued):
Sharing a sentence is not in itself a finding about the gene and the disease.
glioma (continued). "Studies in glioma have shown that miRNA128 regulates BMI-1 mRNA and protein expression by directly targeting the 3′-UTR of BMI-1 mRNA." (PMID 21559395, 2011). "Although some studies have shown that Bmi‐1 is expressed more in high‐grade than low‐grade gliomas, others have noted varying levels of Bmi‐1 expression across glioma grades without a direct correlation with patient's survival." (PMID 39791545, 2025). "Essential for Bmi‐1 expression, HDAC activity can be targeted using vorinostat glioma xenografts." (PMID 39791545, 2025). "For example, Bmi-1 inhibition in colorectal cancer and combined suppression of Bmi-1 and enhancer of zeste 2 Polycomb repressive complex 2 subunit (EZH2) expression in glioma effectively eliminated cancer stem-like cells, thereby achieving an ideal anticancer efficacy." (PMID 37219449, 2023). "Furthermore, the expression of Bmi-1 can activate the NF-κB signaling pathway and increase the expression of vascular endothelial growth factor C (VEGF-C)to promote glioma angiogenesis." (PMID 35897796, 2022). "BMI1 and CD44 were reported to differentiate the mesenchymal molecular subtype from other gliomas." (PMID 33329553, 2020). "Moreover, we displayed that BMI1 and DANCR were negatively correlated with miR-135a-5p in glioma tissues, and DANCR was positively correlated with BMI1." (PMID 32099526, 2020). "Recently, early phase clinical trials have begun to look at the utility of BMI-1 inhibitors in advanced solid tumors (clinicaltrials.gov #NCT02404480), gliomas (clinicaltrials.gov #NCT03605550), and for relapsed/refractory AML (clinicaltrials.gov #NCT03761069)." (PMID 31380371, 2019). "We also confirmed that resveratrol obviously inhibited EMT-induced self-renewal ability of glioma stem cells (GSCs) and inhibited EMT-induced cancer stem cell markers Bmi1 and Sox2, suggesting that resveratrol is able to suppress EMT-generated stem cell-like properties in GBM cells." (PMID 31119150, 2019). "The findings suggested that miR-128-1 could impede the growth of glioblastoma and GSCs via targeting BMI1 and E2F3, so miR-128-1 and DNA demethylating agents were promising for anti-glioma therapy at least in part by eliminating GSCs." (PMID 28947999, 2017). "In addition, the authors demonstrated that Bmi-1 confers resistance to apoptosis in glioma cells via the IKK-NF-kB pathway, suggesting that this is a useful prognostic marker for gliomas." (PMID 26317630, 2015). "Our investigation revealed BMI1 over-expression in 29 of 54 (53.7%) pediatric gliomas, 8 of 8 (100%) patient derived orthotopic xenograft (PDOX) mouse models, and in both CD133+ and CD133− glioma cells." (PMID 25526772, 2014). "To determine whether NF-κB signaling mediates Bmi-1-promoted glioma angiogenesis, we first examined whether Bmi-1 expression enhances the transcriptional activity of NF-κB in LN382T and T98G glioma cells." (PMID 23383216, 2013). "Either a VEGF-C promoter fragment lacking the NF-κB binding site or mutation of the NF-κB binding site in the VEGF-C promoter region showed no NF-κB activity in either Bmi-1-overexpressing and -silenced glioma cells." (PMID 23383216, 2013). "Mutating the NF-kappaB binding site in the MMP-9 promoter abrogated luciferase activity, and a MMP-9 promoter fragment lacking the NF-kappaB binding site displayed no significant change in the luciferase activity in Bmi-1 overexpressing glioma cells." (PMID 22967049, 2012). "By synthesizing the current literature, we aimed to discuss the unique role of Bmi‐1 in regulating gene expression and chromatin structure in GBM, thereby addressing a significant gap in the literature regarding the specific involvement of PRC1, particularly Bmi‐1, in glioma pathogenesis." (PMID 39791545, 2025). "Moreover, Bmi-1 increases luciferase activity of the MMP9 promoter-driven reporter gene containing an NF-κB binding site, which promotes MMP9 transcription levels in glioma cells." (PMID 35897796, 2022).
glioma (continued). "Furthermore, we also analyzed the relationship among miR-135a-5p, DANCR and BMI1, and found that expression levels of BMI1 and DANCR were negatively correlated with miR-135a-5p abundance in glioma tissues, and expression of DANCR was positively correlated with BMI1 level." (PMID 32099526, 2020). "Glioma CSCs may produce VEGF, promoting vessel growth, while endothelial cells cocultured with glioma CSCs, facilitated the CSC-like phenotype of glioma cells by increasing the expression of Sox2, Olig2 and Bmi1." (PMID 30510501, 2018). "Furthermore, IHC analyses demonstrated markedly elevated expression of CD31, enhanced microvascular outgrowth and increased MVD in Bmi-1-overexpressing gliomas, as opposed to those Bmi-1-knockdown gliomas (P<0.05)." (PMID 23383216, 2013). "Furthermore, Bmi1 is required to prevent glial differentiation in SmoM2 induced medulloblastoma, possibly by a similar mechanism of Ezh2 mediated repression of BMPR1A that affects JAK/STAT3 mediated glial differentiation in glioma." (PMID 22574128, 2012). "Bmi-1 may play an important role in the development of aggressive phenotype of glioma via activating the NF-kappaB/MMP-9 pathway and therefore might represent a novel therapeutic target for glioma." (PMID 22967049, 2012). "Knock-down of ROCK1 in glioma cells did not significantly influence EZH2, EGFR, XIAP and BMI1 expression, which indicates miR-340, regulates these oncogenes through distinct mechanisms bypassing ROCK1." (PMID 25831237, 2015). "Transwell migration assay (without Matrigel) revealed that overexpression of Bmi-1 significantly increased the rate of migration of A172 and LN229 glioma cells, as compared with that of control cells." (PMID 22967049, 2012). "Since there are studies suggesting that not all glioma stem cells are CD133+ and our data indicated that BMI1 was also strongly expressed in CD133− pGBM cells, we next examined if CD133− pGBM cells were tumorigenic and if they also depended on BMI1 for tumor formation." (PMID 25526772, 2014).
prostate carcinoma (73 papers, 2008 to 2025). A carcinoma that arises from epithelial cells of the prostate gland. "Ser251, 253, and 255 of Bmi-1 are implicated as potential phosphorylation sites by Akt, and phosphorylation of these sites enhances the oncogenic potential of Bmi-1 in mouse prostate cancer." (PMID 38141761, 2024). "In prostate cancer, reduction or loss of hsa-mir-200b limits the suppression of Bmi-1, which is accountable for abnormal cell proliferation, migration and chemosensitivity." (PMID 36291575, 2022). "Relatedly, EZH2 and BMI1 double-positive prostate carcinomas are associated with metastasis with an increasing likelihood of therapy failure and disease relapse." (PMID 33804165, 2021). "BMI1 is a cancer stem cell marker that has been implicated in acute myeloid leukemia, cervical cancer, and prostate cancer, among others, by acting as a chromatic remodeler of regulatory genes." (PMID 32751422, 2020). "BMI1 is abundantly expressed in prostatic luminal epithelial cells and its levels are associated with poor prognosis of prostate cancer patients." (PMID 29402932, 2018). "Prostate cancer patients with an 11-gene signature, which is associated with BMI1 expression, are more likely to have an unfavorable prognosis when compared to those without this signature." (PMID 19903340, 2009). "PTEN physically associates with BMI1 in cultured prostate cancer cells and appears to co-localize with BMI1 in primary prostate cancer." (PMID 19903340, 2009). "Downregulation of the miR-130b–301b cluster impairs cellular senescence in prostate cancer, while miR-494-3p increases the radiosensitivity of oral squamous cell carcinoma cells through the induction of cellular senescence caused by the downregulation of Bmi1." (PMID 28431583, 2017). "It is negatively controlled by circ_0016068 and then regulates BMI-1 to suppress prostate cancer cell growth." (PMID 35874898, 2022). "As well, BMI1 protein was expressed at high levels in precancerous lesions of prostate cancer (prostatic intraepithelial neoplasias, PINs) and prostate carcinomas, and accompanied by reductions of p16INK4a and p19ARF/p14ARF." (PMID 33804165, 2021). "Both ADAMTS and MMP family members are known to be BMI1 targets in GIC and NPC, as assessed by ChIP Seq, and their predicted upstream regulator, MYC, has also been described to be controlled by BMI1 in prostate cancer." (PMID 34316702, 2021). "Prostate cancer patients with the 11-gene signature of a stem cell-like expression profile, which contains BMI1, are more likely to have a short interval to disease recurrence, distant metastasis, and death after therapy." (PMID 33804165, 2021). "Castration-resistant BMI1+SOX2+ prostate cancer cells play an important role in prostate cancer recurrence." (PMID 33499351, 2021). "In a study of prostate cancer, high BMI1 expression was found to be correlated with unfavorable factors, such as a high Gleason score and extraprostatic extension with prostate-specific antigen recurrence." (PMID 34442383, 2021). "In various cancer types, miR-128 functions as a tumor suppressor, targeting epidermal growth factor receptor in lung cancer, polycomb complex protein BMI1 in prostate cancer, PAICS in bladder cancer, and E2F transcription family member E2F3a in glioblastoma." (PMID 32218208, 2020). "Knockdown of BMI1 in docetaxel resistant prostate cancer cells inhibited the expression of cyclin D1 or BCL2, the downstream targets of the Wnt/β–catenin pathway." (PMID 32726929, 2020). "The overexpression of BMI1 in prostate cancer cells also enhanced the transcriptional activity of TCF." (PMID 32726929, 2020). "Bansal and coworkers showed that BMI1 is overexpressed in populations of CD49highCD29highCD44high enriched in prostate cancer stem-like cells." (PMID 31366128, 2019). "Various mechanisms are responsible for the increased BMI1 expression at the level of prostate cancer stem cells." (PMID 31366128, 2019).
prostate carcinoma (continued). "Our data provide the first experimental proof on the efficacy of combination therapy targeting BMI1 and cell cycle against breast, colon, and prostate cancer." (PMID 31548560, 2019). "Small molecule inhibitors of EZH2 and BMI1, two epigenetic effectors, are available and have shown efficacy in prostate cancer preclinical models." (PMID 31143708, 2019). "Several recent studies have contributed to better define the role of BMI1 in the biology of prostate cancer stem cells." (PMID 31366128, 2019). "For TIBs, few studies have shown that B cells produce lymphotoxin and promote the progress of androgen-resistant prostate cancer by activating the IKKα-BMI1 signal pathway in prostate cancer stem cells under the influence of chemokine CXCL13." (PMID 31662750, 2019). "B lymphocytes recruited by CXCL13 into the tumor site promote castration-resistant prostate cancer by producing lymphotoxin, which activates an IKKα-Bmi1 module in prostate cancer stem cells." (PMID 31395078, 2019). "This discovery conceptually advances our understanding of a novel, PRC1-independent role of BMI1 in prostate cancer progression through the AR pathway." (PMID 29402932, 2018). "In this study, we made the unexpected observation that AR protein levels, but not transcript levels, as well as the protein and transcript levels of AR-activated targets PSA and TMPRSS2, were decreased by depletion of BMI1 in AR-positive prostate cancer cells." (PMID 29402932, 2018). "BMI1 is over-expressed in prostate cancer with adverse pathologic and clinical features and the presence of BMI1 in prostate cancer specimens often indicates metastatic disease and a high probability of unfavorable therapeutic outcome." (PMID 28830551, 2017). "Subsequent studies have shown that BMI-1 regulates the self-renewal and transformation of prostate cancer cells, as well as cell growth and metastasis in renal cancers." (PMID 29299167, 2017). "Overexpression of BMI1 has been detected in several human cancers including head and neck cancer, colorectal carcinoma, non‐small‐cell lung cancer, and prostate cancer." (PMID 28079973, 2017). "Especially, miR-128 plays an important role as a regulator in prostate cancer cell differentiation by inhibiting BMI-1, which plays a role in epigenetic gene silencing and stem cell renewal." (PMID 29299167, 2017). "To assess the ability of Bmi1+ cells to serve as prostate cancer initiating cells, we specifically deleted Pten in Bmi1-expressing cells by treating Bmi1-CreER;R26R-confetti;Ptenf/f mice (hereafter BC-Pten mice) with tamoxifen." (PMID 27703144, 2016). "Several of the identified targets genes are known mediators of prostate cancer cell “stemness” and self-renewal, such as NKx3.1, BMI-1, and SOX-4; some are also embryonic stem cell (ESC) regulators, such as KLF4 and SOX2." (PMID 26046794, 2015). "BMI1 has also been reported to enhance telomerase activity in mammary epithelial cells and prostate cancer cells." (PMID 26633535, 2015). "Bmi1 has also been shown to regulate self-renewal and proliferation of cancer stem cells from other tumor types such as hepatocellular carcinoma, prostate cancer, and pancreatic cancer." (PMID 25348805, 2014). "We also reported that the ability of VEGF/NPR2 to induce BMI-1 expression is FAK-dependent in prostate cancer." (PMID 23436775, 2013). "BMI-1 is crucial to both NSCs and CSCs and, in prostate cancer, is an essential regulator of SC renewal and tumor initiation and progression." (PMID 22472196, 2012). "It has been reported that Bmi1 confers cisplatin and docetaxel resistance in osteosarcoma and prostate cancer, respectively." (PMID 23209748, 2012). "Increases in BMI1 mRNA were detected in prostate cancer cell lines, xenografts and human primary prostate carcinomas, as well as primary prostate tumors derived from the TRAMP transgenic mouse model." (PMID 19903340, 2009).
prostate carcinoma (continued). "PTEN binds to BMI1 in the nucleus of prostate cancer cells and reduces BMI1-mediated suppression of p16INK4A and p14ARF as well as BMI1-mediated enhancement of hTERT." (PMID 19903340, 2009). "We performed double immunofluorescent (IF) staining for PTEN and BMI1 in 42 primary prostate cancer specimens." (PMID 19903340, 2009). "Expression of all three proteins (BMI1, RING1, and EZH2) is associated with adverse pathological features in prostate cancer, but only BMI1 provides additional prognostic power in multivariate analysis." (PMID 19002169, 2009). "In addition, it has been found that the CXCL13 recruits B cells into prostate cancer tumors and activate the IκB kinase α-BMI1 module in cancer stem cells through the production of LT, thus promoting the progression of castration-resistant prostate cancer." (PMID 39744696, 2025). "Additionally, we identified five downstream genes (IGF1R, BMI1, RHAMM, NuSAP1, and PBK) of E2F1 in prostate cancer, and these genes are associated with the survival and proliferation of prostate cancer." (PMID 38374143, 2024). "RING1B and BMI1 (also known as PGCF4) are all closely related to prostate cancer." (PMID 38093337, 2023). "Furthermore, Ser255 was found to be the site of O-GlcNAcylation of Bmi-1 in prostate cancer, and O-GlcNAcylation of Bmi-1 promoted the stability of Bmi-1 protein and its oncogenic activity." (PMID 35897796, 2022). "In addition, a series of molecules, including CD44, CD133, integrin α2β1, ALDH1A1, and Bmi1, involved in the regulation of cancer stem cell self-renewal, metastasis, and drug resistance, have also been confirmed in prostate cancer." (PMID 35965510, 2022). "Most reports focused on the role of Bmi-1 in the development of prostate cancer." (PMID 33584271, 2020). "BMI1 is overexpressed in prostate cancers associated with negative pathologic and; the presence of BMI1 expression is predictive of disease recurrence." (PMID 31366128, 2019). "Importantly, BMI1 was found to be particularly expressed at the level of a subpopulation of prostate cancer cells, displaying properties of tumor-initiating cells." (PMID 31366128, 2019). "A recent study showed that the protein product of the developmental gene BMI-1 (B cell-specific Moloney murine leukemia virus integration site 1) could be stabilized through O-GlcNAc modification at S255 in prostate cancer." (PMID 31272438, 2019). "Since both BMI1 and AR are abundantly expressed in prostate cancer cells, whether BMI1 modulates AR protein expression and transcriptional activity remains unclear." (PMID 29402932, 2018). "Interestingly, recent studies have also identified distinct castration-resistant progenitors that express Bmi1 (CARBs) that are cells of origin for prostate cancer." (PMID 29334357, 2018). "The polycomb group protein BMI1 is highly expressed in prostate cancer." (PMID 29402932, 2018). "BMI1 is upregulated in multiple types of cancer, including prostate cancer." (PMID 29402932, 2018). "The ZEB1-AS1-ZEB1-miR200c-BMI1 pathway may be an important part of the dysfunctional regulatory network in prostate cancer." (PMID 28830551, 2017). "Furthermore, miR-128 has anti-proliferative and anti-tumorigenic effects on diverse cancer types that show overexpression of BMI-1, including prostate cancer and breast cancer." (PMID 29299167, 2017). "BMI1 is frequently overexpressed in human myeloma, prostate cancer, and lung cancer." (PMID 27166996, 2016). "Erismodegib (a Shh signaling pathway inhibitor) could inhibit EMT and human prostate cancer stem cell growth in NOD/SCID IL2Rγ null mice by regulating Bmi-1 and microRNA-128." (PMID 25943311, 2015). "Over-expression of Bmi1 has been found in a large number of human cancers, and a set of 11 genes which make up the Bmi1 signature has been defined in colorectal, breast, lung and prostate cancers." (PMID 24559156, 2014).